PLK1 (polo like kinase 1)
Diseases named in the same sentence as PLK1 in open-access papers (continued):
Sharing a sentence is not in itself a finding about the gene and the disease.
breast carcinoma (continued). "MDM2 ligase, coupled with inhibitors of the targets BCL2L1, BRD4, CDK9, PLK1 and MCL1 in stomach cancer, and MDM2 with PIK3C3 inhibitors in breast cancer seemed to be the best therapeutic construction." (PMID 35249548, 2022). "MDM2 ligase coupled with inhibitors of the targets BCL2, BRD4, CDK9, PLK1 and MCL1 in stomach tumor, and MDM2 with PIK3C3 inhibitors in breast cancer, seems to be the best therapeutic strategy." (PMID 35249548, 2022). "The most common breast cancer subtype is Luminal A; NHB women with Luminal A breast cancers significantly overexpress PLK1, AURKB, and NDC80, while TBK1 is significantly overexpressed in Luminal A breast cancers from NHW women." (PMID 36494865, 2022). "MiR-183-5p, reported to be aberrantly expressed in breast cancer, directly binds to the 3′UTR of PLK1, effectively downregulating its expression." (PMID 34561554, 2022). "The PLK1 inhibitor BI2536 enhances the effect of paclitaxel on MCF‐7 and T‐47D breast cancer cells, by inducing their apoptosis, whereas it prevents tamoxifen‐induced senescence." (PMID 36065138, 2022). "This analysis indicates that the mRNA levels of multiple mitotic regulators, including TTK, Nek2, PLK1, Cyclin B1, BUB1, Aurora kinases A and B, and NDC80 (also known as HEC1) are elevated in breast cancers in NHB women." (PMID 36494865, 2022). "This paradox stimulated us to investigate the functions of PLK1 and PLK2 in breast cancer, as well as potential translational implications." (PMID 35156101, 2021). "Although PLK2 belongs to the same family as PLK1, and both kinases are implicated in cell-cycle progression, recent studies as well as our data presented herein suggest that PLK2 may actually be a tumor suppressor that is silenced in many types of cancers, including breast cancer." (PMID 35156101, 2021). "Plk1 expression correlated with HIF-2 targets in ccRCC and in testicular adenocarcinoma, with HIF-1α and HIF-2α targets in 6 out of 26 cancer types like breast cancer, liver cancer, and sarcoma." (PMID 33547392, 2021). "In the selected key specific DEGs for Basal-subtype breast cancer, the altered expression of SOX11, PLK1, BUB1, OGN, COL4A6, AGTR1, and ADRB2 were significantly correlated with the prognostic survival of the patients." (PMID 33644115, 2021). "We previously demonstrated that forced downregulation of miR-10b-3p in breast cancer perturbed BUB1, PLK1, and CCNA2 expression, hence accelerated tumor progression." (PMID 33230261, 2021). "PLK-1 is a conserved kinase mainly involved in the regulation of cell cycle and increased expression of PLK-1 was described in breast cancer, lung cancer and lymphoma, among others, and is being considered a potential molecular target in anti-cancer therapies." (PMID 35008260, 2021). "Both the cytoplasm and nucleus of ovarian and breast cancer cells can express CDK1, CHK2, PLK1, and Aurora A. CHK1 and pCDC25CSer216 were located only in the cytoplasm." (PMID 32393310, 2020). "For breast cancer, the differences of CDC25C (P = 0.001), CDK1 (P = 0.000), CHK1 (P = 0.001), CHK2 (P = 0.000), PLK1 (P = 0.000) and Aurora A (P = 0.000) expression between primary cancer with and without metastasis also had statistical differences." (PMID 32393310, 2020). "Here, the authors demonstrate that PLK1 inhibition is a potential therapeutic target in CCND1-driven and in RB-positive Palbociclib-resistant breast cancers." (PMID 32792481, 2020). "Later, it was verified by qRT-PCR analysis that CDK1, PLK1, and CDC20 were the direct targets of podophyllotoxin in breast cancer cells." (PMID 32848800, 2020).
breast carcinoma (continued). "We tested two predicted OCN pairs in each cancer type, including NCSTN and DNM1, and NCSTN and OGT in liver cancer; CCNA2 and PTP4A1, and HIF1A and PARP1 in lung cancer; and CCNA2 and PTP4A1, and PLK1 and PTP4A1 in breast cancer." (PMID 31097707, 2019). "Immunohistochemistry was performed using antibodies to PLK1, MDM2 and Ki67 on Tissue Micro-Array (TMA) slides of a cohort of 215 primary breast cancers." (PMID 22405092, 2012). "Here, we document that down-regulation of miR-10b* correlates with aberrant expression of PLK1, BUB1 and CCNA2 proteins in breast cancer specimens when compared to their matched peritumoural samples." (PMID 23125021, 2012). "Restoration of miR-10b* expression by using mimic 10b* reduces PLK1, BUB1 and CCNA2 protein expression in diverse breast cancer cell lines." (PMID 23125021, 2012). "CCNB1 mRNA expression has been reported to be significantly and positively correlated with mRNA expression levels of CENPE, AURKB, PLK1, and PLK4 in both breast tumors and breast cancer cell lines." (PMID 21445301, 2011). "In breast cancer, there is also evidence that the CDK1/CCNB1/PLK1 axis may be one of the potential pathways by which KIF2C affects tumor progression." (PMID 41333555, 2025). "PLK1 can also exert a synergistic effect with FOXM1 to affect the prognosis of liver cancer, papillary thyroid cancer, bladder cancer,diffuse large B-cell lymphoma, kidney cancer, lung cancer, breast cancer, esophageal cancer and other tumors." (PMID 40612941, 2025). "More importantly, PLK1 overexpression significantly attenuated the tumor-suppressive effects of SAMD5 overexpression on aggressive breast carcinoma cell phenotypes, suggesting that PLK1 mediates the functions of SAMD5 in breast cancer." (PMID 39524172, 2024). "The results showed that the expression of PLK1 and IFNG in human breast cancer cells were significantly higher than in human normal mammary epithelial cells; while the expression of S100B and IRS2 were significantly lower than in human normal mammary epithelial cells." (PMID 39314848, 2024). "In our study, results from multiple research methods illustrate that LAS induces cellular G2/M blockade to trigger apoptosis via downregulating the PLK1 pathway, which suggests LAS could be a promising therapeutic agent for treatment of breast cancer." (PMID 38495493, 2024). "In vivo studies using a xenograft tumor model in nude mice demonstrated that SAMD5 overexpression reduced tumor weight and volume, with these effects being partially reversed by PLK1 overexpression, highlighting the interaction between SAMD5 and PLK1 in modulating breast carcinoma progression." (PMID 39524172, 2024). "However, there are no comprehensive studies investigating the crosstalk between PLK1 and PI3K pathways in breast cancer." (PMID 39409880, 2024). "Regarding cell phenotypes, PLK1 overexpression facilitated cell viability, colony formation, and invasive capability; additionally, PLK1 overexpression partially attenuated the effects of SAMD5 overexpression on cell viability, colony formation, and cell invasion in breast cancer cells." (PMID 39524172, 2024). "Mechanistic analyses identified a negative correlation between SAMD5 and Polo-like Kinase 1 (PLK1), a gene frequently overexpressed in breast cancer, particularly in TNBC." (PMID 39524172, 2024). "As shown by IHC staining and RT-qPCR, PLK1 expression was higher in breast cancer tissues compared to adjacent non-tumor tissues." (PMID 39524172, 2024).
breast carcinoma (continued). "Thus, PLK1 represents a clinically relevant target in HER2+ breast tumors and its inhibition sensitizes multiple fibroblast-protected HER2+ breast cancer cell lines to lapatinib." (PMID 39513002, 2024). "PLK1 and AURKB are more highly overexpressed in basal breast cancers from NHB." (PMID 36494865, 2022). "To validate the role of PLK1 as a negative prognostic indicator in breast cancer, we used KM Plotter to interrogate publicly available microarray repositories for breast cancer patients." (PMID 35454120, 2022). "The same MCF-7 breast cancer cell line was used to reveal the UA modulating activity on the PLK1, IKK/NF-kB, and BRAF/ERK pathways; UA induced MCF-7 cells apoptosis by suppressing the phosphorylation of BRAF, ERK1, and PLK1 levels." (PMID 35887090, 2022). "The results indicated that CCNB1 and PLK1 expression level in stage III were higher than other stages, suggesting they might play special roles in the development of breast cancer, especially in stage III." (PMID 35456460, 2022). "Rsk and Plk1 both suppress DNA-damage checkpoint signaling by phosphorylating and inhibiting MRE11 activity, whilst FGFR2 regulates MRE11 expression through the MEK/ERK/POU1F1 pathway in breast cancer." (PMID 33927349, 2021). "Strong linkage between these well-studied breast-cancer-related genes and other identified genes makes the identified, but under-studied, genes more reasonable targets for further experimental investigation, such as BTRC and PLK1." (PMID 34290286, 2021). "In brief, the analytical data suggest that SOX11, PLK1, and BUB1 may be involved in tumorigenesis to improve OS of patients with Basal-subtype breast cancer." (PMID 33644115, 2021). "The apparent paradox that PLK1 and PLK2 might exert opposite roles in breast cancer led us to study potential links between PLK2 and PLK1." (PMID 35156101, 2021). "Moreover, in vitro studies in breast cancer cell lines demonstrated that BUB1, like other mitotic regulators such as AurA and Plk1, is involved in the maintenance of CSC and represents a target for developing anti-CSC therapies." (PMID 34064009, 2021). "Finally, we looked at PLK1 expression in CCND1-amplified as compared to CCND1-diploid tumours in the TCGA and Metabric breast cancer datasets." (PMID 32792481, 2020). "Shannaiphenol induces apoptosis by inhibiting the expression and function of the estrogen receptor ERα, lowering the expression of polo-like kinase 1 (PLK-1), and exciting continuously ERK signaling paths to inhibit the proliferation of MCF-7 cells in human breast cancer." (PMID 33265939, 2020). "ZNF695 was also shown to upregulate cell cycle progression genes (e.g., CDK1, PLK1) cooperatively with other master regulators in nonluminal breast cancers." (PMID 30444046, 2019). "Moreover, downregulation of FBXW7 in MDA-MB-468R breast cancer cell induced resistance to the drug paclitaxel by the accumulation of its substrates myeloid cell leukemia 1 (MCL-1) and polo-like kinase 1 (PLK1)." (PMID 30791487, 2019). "PLK1 is overexpressed in several tumor types, including breast cancer, non-small cell lung cancer (NSCLC), and colorectal cancer, and elevated PLK1 has also been correlated with poor prognosis in NSCLC and breast cancer patients." (PMID 29535822, 2018). "Resveratrol impaired the proliferation of breast cancer cells by inducing the hypermethylation of the promoters of the genes of Aurora protein kinase (AURKA) and the Polo-like kinase-1 (PLK1) and consequently decreased its expression, reinforcing the potential role of resveratrol in cancer therapy." (PMID 30627525, 2018). "The effects of treatment with Sepin-1 that are similar on the four breast cancer cell lines include non-activation of caspases 3 and 7 and downregulation of cell cycle-driving proteins, such as Raf, FoxM1, Plk1, Cdk1, Aurora A, Lamin B1, and pericentrin." (PMID 29780443, 2018).
breast carcinoma (continued). "The fact that multiple different tumorigenic behaviors were affected by perturbing CEP55 expression suggests that, like other mitotic proteins [e.g., Aurora‐A, Eg5, PLK1, NEK2], it could regulate multiple aspects of breast cancer development." (PMID 30108112, 2018). "Consistent with this, we have shown that the small molecule inhibitors GSK462364, GSK923295, and GSK1070916 that target the network proteins PLK1, CENPE, and AURKB/C, respectively, inhibit the growth of breast cancer cell lines with high MNAI at lower concentrations than cell lines with low MNAI." (PMID 27368372, 2016). "To further investigate whether FBXW7 expression correlated with its substrates in breast cancer tissues, we decided to study the protein levels of Cyclin E, MCL1, AURKA and PLK1 in these samples." (PMID 27409838, 2016). "The homing ability of subcutaneous ASCs toward the breast cancer cell lines MCF-7 and MDA-MB-231 showed a significant decrease even after the short time treatment with Plk1 inhibitors, supporting the results of the impaired migration behavior obtained by the single cell tracking assay." (PMID 27713178, 2016). "The inhibition of PLK1 led to significant growth inhibition, either alone or in combination with other drugs, on different breast cancer cells and TICs, making them promising therapeutic targets in the treatment of TNBC and other breast cancers." (PMID 22309939, 2012). "Expression of the genes in the PLK1-MCM complex-SKP2 subnet of breast cancer patient datasets is up regulated in ER negative samples; expression of the genes in the PLK1-MCM complex-SKP2 subnet of NSCLC patient dataset is up regulated in lung cancer samples." (PMID 22838965, 2012). "The coordination of PLK1, MCM complex and their interacting genes might driver DNA replication forward, overcoming the effects of replication stress in breast cancer and lung cancer cells." (PMID 22838965, 2012). "Ninety genes belonging to the GO category of 'apoptosis', including members of the BAG family (BAG1, BAG2, BAG3), as well as members of the breast cancer 'proliferation signatures' (BUB1, PLK1, CCNE1, CCND1 and CCNB1) were also identified as up-regulated in our DTET." (PMID 17014703, 2006). "Apart from the Co115 cell line and contrary to our observations in various breast carcinoma cells lines, however, Plk1 was found to be up-regulated rather than down-regulated upon irradiation." (PMID 16887021, 2006). "Thus, unlike most breast cancer cells that have extensive aneuploidy, these PLK1-overexpressing cells serve as an excellent model system for inducing genome instability and subsequently identifying related SDL interactions." (PMID 40347943, 2025). "This could involve techniques such as quantitative PCR, Western blotting, or immunohistochemistry to confirm the overexpression of CHEK1 and PLK1 at both mRNA and protein levels in TNBC tissues compared to normal breast tissues and other breast cancer subtypes." (PMID 39473450, 2024). "This analysis sought to confirm the specific upregulation of CHEK1 and PLK1 in TNBC, as suggested by the initial microarray findings and cross-platform verification analysis, and to contextualize their expression within the broader landscape of breast cancer subtypes." (PMID 39473450, 2024). "Thus, the synergy between L1 and Plk1 inhibitor is more effective in the breast cancer cell line CAL51 than in the non-cancer cell line MCF-10A." (PMID 34493069, 2021).
breast carcinoma (continued). "Disorders in cell-cycle-related pathways have key influences on breast cancer prognosis, and our feature selection result highlights that CDK1, CDK4, AURKA, and PLK1 may play vital roles in the complex cell cycle regulatory network, which in turn affects breast cancer prognosis." (PMID 34290286, 2021). "SOX11, PLK1, BUB1, OGN, COL4A6, AGTR1, and ADRB2 may be involved in the recurrence of Basal-subtype breast cancer, and to some extent the PLK1, BUB1, OGN, COL4A6, AGTR1, and ADRB2 can be used as the specific prognostic markers for Basal-subtype breast cancer." (PMID 33644115, 2021). "However, the biological functions of circRNA polo-like kinase-1 (circPLK1) in the tumorigenesis of breast cancer (BC) and its potential mechanisms have not been well elucidated yet." (PMID 33298061, 2020). "Importantly, a potent PLK1 inhibitor, volasertib (BI6727), has been recently approved for the treatment of acute myeloid leukemia and would be a promising therapeutic agent against palbociclib-resistant breast cancer." (PMID 32344635, 2020). "In this CGH analysis the authors show that, indeed, in breast cancer, there is amplification of the 20q and 16p regions (AURKA and PLK1) whereas the 4q region is often deleted, indicating that downregulation of MAP9 (4q32.1) could be the result, at least in part, of a gene loss." (PMID 24876664, 2014). "However, whether PLK1 blockade is effective in abemaciclib- or ribociclib-resistant ER+ breast cancer has not been described previously." (PMID 40764324, 2025). "Furthermore, we compared enrichment of known ERα transcriptional targets specific to normal breast or breast cancer in the RigoSig gene set and found ERα targets from normal breast to be significantly enriched upon PLK1 inhibition, while ERα breast cancer targets were not." (PMID 36008466, 2022). "Furthermore, when analyzing the association of palbociclib activity and PLK1 mRNA expression in 38 breast cancer cell lines using Cancer Cell Line Encyclopedia (CCLE) data, the current study found that cells with low palbociclib activity (IC50 > 500 nM) had higher PLK1 expression (p = 0.006)." (PMID 35008374, 2022). "Given this synergistic effect, we decided to investigate how a breast cancer cell line and a non-cancer cell line responded to a combination of the four potent anti-microtubular drugs together with inhibitors of the mitotic kinases—Plk1, Aurora kinase and cyclin-dependent kinases (CDKs)." (PMID 34493069, 2021). "Indeed, RPPA data revealed an enrichment of cell cycle‐related genes including CDC25C and PLK1 in proteins downregulated by metformin, echoing a previous report showing selective translational inhibition of cell cycle regulators such as cyclin E2 and ODC1 by metformin in breast cancer cells." (PMID 30221473, 2018). "To evaluate the relevance of our findings in breast cancer patient samples, we mined the expression of PLK1 from the METABRIC dataset and observed that PLK1 is mostly expressed in patients with ERα negative and basal/claudin-low tumours." (PMID 36008466, 2022). "PLK1 does not like in all breast cancer that low expression predicted high RFS and OS (p < 0.05), PLK1 overexpression improved prognosis in Basal-subtype breast cancer (p < 0.05)." (PMID 33644115, 2021). "In ductal breast cancer, we found a grade-dependent increase of AURKA expression (P > 10−3), while the variations of expression of MAP9 and PLK1 are not significant (P > 0.2)." (PMID 24876664, 2014). "For example, breast cancer patients with concomitant expression of Plk1 and the Estrogen Receptor (ER+) have a significantly worse relapse-free survival (RFS) index when compared to ER+ patients that have little or no Plk1 expression." (PMID 30862113, 2019).